CRP (C-reactive protein)
Diseases named in the same sentence as CRP in open-access papers (continued):
Sharing a sentence is not in itself a finding about the gene and the disease.
Sepsis (continued). "Clinical sepsis diagnosis was associated with an increase in biomarkers value over the 3 days preceding this diagnosis [PSP (p = 0.003), PCT (p = 0.025) and CRP (p = 0.009)]." (PMID 33879189, 2021). "We used a machine learning approach to predicting, observed an increase in the probability of developing sepsis when IG and CRP were higher than 6% and 160 mg/L, respectively." (PMID 34915849, 2021). "At 24 h after initial evaluation, the best variables to identify sepsis were C-reactive protein > 0.75 mg/dl, neutrophil-to-lymphocyte ratio > 1.5 and sick-appearance at 24 h." (PMID 34490157, 2021). "Before these recent studies, C reactive protein (CRP) has been widely used as a marker of sepsis in dogs and remains to date the most used in routine practice." (PMID 34072427, 2021). "Increased PCT and CRP sends an alarm to physicians that patients should be in a later phase of sepsis compared to increased MDW." (PMID 34442376, 2021). "Serum procalcitonin (PCT) and high-sensitivity C-reactive protein (hs-CRP) are still the gold standard inflammatory markers in the current sepsis guidelines." (PMID 34310652, 2021). "A novel self-propelled micromotor-based immunoassay (MIm) has been used for C-reactive protein (CRP) detection of blood of preterm infants suspected to have sepsis." (PMID 34834328, 2021). "CRP is one of the stronger sepsis markers in the dataset used to train the SF model and although SF performs better than any single data item it is to be expected that more CRP measurements would have improved the performance of SF." (PMID 34425790, 2021). "Procalcitonin and C-reactive protein, biomarkers increasingly utilized in sepsis triage, are widely available but have variable utility in Southeast Asia for infection prognosis." (PMID 32034914, 2021). "CRP not only has lesser sensitivity and specificity for sepsis diagnosis than PCT but it also has a slower descent pattern in comparison to PCT." (PMID 34912626, 2021). "Procalcitonin (PCT) and C-reactive protein (CRP) have perhaps been the most widely used, but they have limited ability to distinguish sepsis from other inflammatory conditions or to predict outcomes." (PMID 33869250, 2021). "A meta-analysis of the accuracy of the CRP test for neonatal septicemia found an overall sensitivity of 71% and specificity of 86% in the diagnosis of NS." (PMID 34912626, 2021). "The diagnostic performance of progranulin to differentiate between sepsis and the distractors was comparable to that of procalcitonin, and generally better than the proinflammatory markers C-reactive protein and interleukin-6." (PMID 34476621, 2021). "Magnetic nanoparticles were also considered to construct a biosensor that was used to sense CRP for the characterization of sepsis and necrotizing enterocolitis with an LOD of 0.6 pg mL−1." (PMID 33717630, 2021). "During hospitalization, the patient experienced seven episodes of sepsis characterized by hyperpyrexia and elevated C-reactive protein (CRP), which in many occasions were accompanied by increased numbers of white blood cell (WBC) and neutrophils." (PMID 34975848, 2021). "On the other hand, highly sensitive CRP, which is the standard sepsis biomarker used in our NICUs, has become available in various clinical laboratories." (PMID 34691286, 2021). "Previous studies have shown that PCT and CRP concentrations are related to the prognosis of patients with sepsis." (PMID 34133658, 2021). "The median CRP in those with sepsis was 121mg/dl and CRP/Albumin among septic patient was found to be 3.4." (PMID 35199783, 2021). "The ROC curve was used to evaluate the diagnostic value of PCT, CRP, PCT/Alb, and CRP/Alb in the poor prognosis of patients with sepsis-induced AKI." (PMID 34141715, 2021). "This LOD is lower than the cutoff value of 40–200 μg/mL for accurate CRP detection to diagnose sepsis, demonstrating the effectiveness of the proposed GMR biosensing system for this application." (PMID 34940280, 2021).
Sepsis (continued). "It has more sensitivity early in sepsis than CRP, thereby ensuring a definitive diagnosis, reducing hospital stay, antibiotic overuse, and microbial resistance." (PMID 34912626, 2021). "In particular, the clinical detection of CRP can be predominately employed to guide antibiotic treatment for sepsis, thus avoiding the disproportionate and excessive usage of antimicrobials." (PMID 33717630, 2021). "Although C-reactive protein, procalcitonin, and lactate are popular biomarkers of sepsis, their use in guiding emergency care of cancer patients with infections is unclear." (PMID 34439240, 2021). "The interaction plot of IG% and C-reactive protein showed an increase in sepsis probability at an IG% of 6% and C-reactive protein of 160 mg/L." (PMID 34915849, 2021). "This diagram reflects the period of CRP values from 1 h after admission to 21 days after admission; interestingly, the threshold for sepsis at 8 h is CRP 9.9." (PMID 34884171, 2021). "In this regard, measurements of serum biomarkers, such as PCT, CRP, interleukin-6, neopterin, and pro-adrenomedullin, are useful in the diagnosis and management of sepsis." (PMID 33810263, 2021). "The value of CRP in diagnosing sepsis in neonates has been debated and previous studies have indicated that neonates with culture-proven bloodstream infection can have low levels of CRP." (PMID 33546759, 2021). "Endothelial cells produce enhanced levels of PAI-1 in response to C-reactive protein (CRP), which is a proinflammatory marker in critically ill patients such as sepsis patients." (PMID 33937363, 2021). "There is emerging evidence on the role of C-reactive protein to albumin ratio (C-reactive protein/Albumin) in predicting outcomes in patients with critical illness and sepsis, admitted to intensive care unit." (PMID 35199783, 2021). "CRP was positive in 24/28 (85.7%) cases of group A (proven sepsis), and 58/72 (80.5%) cases of group B (probable sepsis) and had a specificity of 95.0%." (PMID 34899922, 2021). "The current study shows for the first time that both salivary IL-10 and CRP/MPV showed statistically significant differences between neonates with late-onset sepsis and controls." (PMID 34676267, 2021). "To determine the ability of the CRP adsorbent PentraSorb to deplete soluble CRP as well as CRP+ EVs in vitro, we selected plasma samples from specific sepsis patients that contained at least 50% of CRP+ EVs (n = 6)." (PMID 33772103, 2021). "The differences were analyzed using the Mann–Whitney U-Test; binary logistic regression was used to determine the dependency of prediction, and the Closest Top-left Threshold Method presented time-specific thresholds at which CRP is predictive for sepsis." (PMID 34884171, 2021). "Among the numerous biomarkers recommended for predicting sepsis, CRP and PCT are the most widely used in clinical practice." (PMID 33857210, 2021). "CRP levels were shown to be reduced rapidly by HDIVC (200 mg/kg/day) in a previous before-after study in a cohort of sepsis patients." (PMID 33967773, 2021). "On the other hand, especially in burns, where early sepsis diagnosis and initiation of therapy is key to survival, clinicians include pro-inflammatory biomarkers like C-reactive protein (CRP) or procalcitonin (PCT) into their decision-making process." (PMID 34442346, 2021). "C-reactive protein and procalcitonin, currently used as sepsis biomarkers, are influenced by several maternal and fetal pro-inflammatory conditions in the perinatal age." (PMID 34830040, 2021). "Similar to our findings, CRP was recently reported to be increased in EVs of patients with sepsis and to promote proinflammatory responses in macrophages." (PMID 34576246, 2021). "The observed longitudinal changes of plasma lEVs concentration is similar to many biologically active compounds with elevated levels during sepsis (e.g., c-reactive protein, interleukin 6)." (PMID 34604260, 2021).
Sepsis (continued). "Levels of miR-25 was negatively associated with the severity of sepsis, SOFA score, CRP and PCT level, 28-day deaths, and levels of oxidative stress indicators." (PMID 34956235, 2021). "Traditionally, serum CRP is measured as part of the initial investigations in sepsis diagnosis and is used as a rapid test to guide management in infants with suspected LOS." (PMID 34522543, 2021). "CRP and lactate levels [IQR] were higher in the sepsis group than in the non-sepsis group (CRP: 176.5 mg/L [148.6–221.8] vs. 77.8 mg/L [33.2–143.6] and lactate: 4.9 mmol/L [3.5–6.4] vs. 2.8 mmol/L [2.2–4.7], respectively, all P < 0.001)." (PMID 34915849, 2021). "By a single UV‐light source, both CRP and IL‐6 were quantified with 42.5 × 10−9 and 0.21 × 10−12m detection limits, respectively, values which are within the clinical range observed in sepsis." (PMID 33236524, 2021). "Herein, we aimed to explore the values of PCT and CRP as well as the ratios of PCT/Alb and CRP/Alb in the poor prognosis of patients with sepsis-induced AKI." (PMID 34141715, 2021). "PCT is a good biomarker of sepsis and increases earlier than CRP; it also has an advantage in managing antibiotics." (PMID 33857210, 2021). "Another study suggested that both CRP and IL-6 more accurately identified severe sepsis and septic shock than sTREM-1, although sTREM-1 did outperform PCT in diagnosing severe sepsis." (PMID 33803628, 2021). "CRP is an acute-phase inflammatory serum protein that is reactive to sepsis and can be suppressed through effective antimicrobial therapy or surgical treatment." (PMID 33869237, 2021). "CRP (C-reactive protein) is one of the most basic biomarkers indicating mortality in patients with sepsis and intensive care unit (ICU)." (PMID 34784756, 2021). "Nanomaterial-inspired nanodiagnostic platforms contribute accurate and rapid detection of sepsis-associated biomarkers such as live bacteria, CRP, PCT, and cytokines, satisfying the needs of point-of-care diagnosis for timely warning of sepsis progression." (PMID 33717630, 2021). "An example of this is miR-495, which is significantly downregulated in patients with sepsis and negatively correlated with CRP and PCT." (PMID 33654698, 2021). "Variables that remained independently associated with death in males included age >70 years, public insurance, incremental increase in quick sepsis-related organ failure assessment (qSOFA) and C-reactive protein (CRP), lymphocytopenia, and thrombocytopenia." (PMID 36168478, 2021). "Compared to other traditional biomarkers, such as procalcitonin and C-reactive protein, LBP has a moderate degree of diagnostic accuracy for sepsis." (PMID 35005033, 2021). "In humans undergoing sepsis or septic shock, CRP is known to activate the complement system and increase antigen presentation." (PMID 34937173, 2021). "The 3 single predictors for sepsis with the highest OR's were sick appearance (OR 171.5, 95% CI, 22.1–1,330.5), CRP > 0.75 mg/dl (OR 62.0, 95% CI, 15.9–242.0) and NLR > 1.5 (OR 212.5, 95% CI, 12.4–3,650.1)." (PMID 34490157, 2021). "Urinary C-reactive protein, urinary leucine-rich alpha glycoprotein-1 and urinary SAA have diagnostic value in cases of sepsis." (PMID 34675320, 2021). "On this plot, when the IG% increased above 6% and the CRP level was above 160 mg/L, the probability of sepsis increased significantly, above 0.4." (PMID 34915849, 2021). "The routinely used combination of inflammatory markers PCT and CRP together with clinical signs and tissue perfusion parameters (lactate, pH, base deficit) provide solid information about the clinical course of sepsis." (PMID 33923419, 2021). "Mortality, disease severity scores, heart rate, CRP, and lactate were higher in sepsis compared to traumatic SIRS (p < 0.05)." (PMID 33441606, 2021). "NEAT1 showed a good predictive value for increased sepsis risk.NEAT1 expression was positively associated with disease severity, CRP, PCT, TNF-α, and IL-1β, 28-day deaths." (PMID 34956235, 2021).
Sepsis (continued). "The parameters commonly used to monitor inflammation process and sepsis evolution are lactate, C-reactive protein, procalcitonin, and, more recently, TNF, IL-1beta, and IL-6." (PMID 33685484, 2021). "The current study shows for the first time that both salivary IL-10 and CRP/MPV ratio showed statistically significant differences between neonates with late-onset sepsis and controls." (PMID 34676267, 2021). "Diagnostic performance of WBC count, CRP, PCT, and MDW in predicting sepsis (by Sepsis-3 definition)." (PMID 33857210, 2021). "As shown by the threshold values, the CRP value at 8 h is quite low, but it is an independent predictor for the development of sepsis." (PMID 34884171, 2021). "In several species, it has already been proved that sepsis induces an acute phase reaction, that in turn is characterized by an increase of acute phase proteins such as CRP, and by oxidative phenomena." (PMID 34072427, 2021). "Sepsis odds also increased with leukopenia (OR 1.790, 95% CI 1.04-3.082), increase in C-reactive protein (OR 1.028, 95% CI 1.016-1.040) and decrease in platelets count (OR 0.992, 95% CI 0.989-0.994)." (PMID 34107906, 2021). "On ROC curve analysis PCT clearly outperformed TLC and CRP for diagnosis of sepsis with AUC 0.78 (95%CI, 0.697- 0.865)." (PMID 34912433, 2021). "Multivariate logistic regression analysis of predictive values of PCT, PCT/Alb, CRP, and CRP/Alb in patients with sepsis-induced AKI." (PMID 34141715, 2021). "The AUC for sepsis detection using MDW combined with WBC was similar to CRP alone (0.85 [0.83–0.87]) and exceeded that of PCT." (PMID 34193208, 2021). "In recent years, PCT, interleukin-6 (IL-6), HBP, C-reactive protein (CRP), serum resistin, and other indicators have been used clinically to assess the severity and prognosis of sepsis." (PMID 34514164, 2021). "Inflammatory markers include white blood cell count, lactate dehydrogenase, C-reactive protein, fibrinogen, and D-dimer, which are commonly used in clinical practice to monitor the process of sepsis." (PMID 33685484, 2021). "Research works have shown the sequential organ failure assessment (SOFA) score and C-reactive protein (CRP) to be effective prognostic tools in the management of sepsis, infections as well as patients with IE." (PMID 33869237, 2021). "Our findings confirm a high degree of interaction of EVs with CRP in sepsis patients and provide evidence for the efficient depletion of both, soluble and EV-associated CRP using PentraSorb." (PMID 33772103, 2021). "The adjusted median concentrations of urinary C-reactive protein were 1337.6, 358.7, and 2.4 in the sepsis, SIRS, and healthy control groups, respectively." (PMID 34675320, 2021). "Development of nanosensors based on electrochemical, immunological or magnetic principals provide highly sensitive, selective and rapid detection of sepsis biomarkers such as procalcitonin and C-reactive protein and are reviewed extensively." (PMID 33413364, 2021). "In this regard, several reports have shown that IL-6 is a useful biomarker for detecting early sepsis; however, CRP and PCT are still often within the reference range owing to their much slower rates." (PMID 34749673, 2021). "We found significantly elevated levels of both, total EVs (Anx5+) and EVs carrying CRP (CRP+Anx5+) in sepsis patients as compared to healthy individuals, where CRP+ EVs remained undetectable." (PMID 33772103, 2021). "Clinical sepsis diagnosis was associated with an increase in biomarkers over the 3 days preceding this diagnosis: PSP (p = 0.003), PCT (p = 0.025) and CRP (p = 0.009)." (PMID 33879189, 2021). "This study was conducted to investigate the predictive role of C-reactive protein-to-albumin ratio (CAR) for sepsis and prognosis in severe burns." (PMID 33833617, 2021).
Sepsis (continued). "The patients were grouped according to sepsis, and the CRP was analyzed according to the point of time at which the value was acquired (1, 2, 3, 4, 6, 8, 12, 24, and 48 h and 3, 4, 5, 7, 10, 14, and 21 days)." (PMID 34884171, 2021). "CRP level varied significantly during the observation period (H = 178.8; p = 0.0001), but the elevation was significant only during sepsis and at two years." (PMID 34869619, 2021). "At the same time,we found that the gut shannon diversity index in children with sepsis was positively correlated with the increase in blood CRP." (PMID 33898360, 2021). "In this study, LPS-induced sepsis was demonstrated in piglets by blood biomarkers for diagnosis of sepsis (total white blood cell count, serum CRP, and PCT)." (PMID 33431831, 2021). "Serum creatinine and CRP levels were significantly higher in sepsis group than the other two groups (p < 0.05)." (PMID 34666725, 2021). "Clinical characteristics and other laboratory markers associated with sepsis, including WBC, procalcitonin, and C-reactive protein, were compared with the IG% values." (PMID 34915849, 2021). "A Brazilian study that used universal primer (q-CRP) showed positivity in all patients diagnosed with clinical sepsis, and in 97% of the studied patients, the DNA of one or more among the seven analyzed bacteria was found." (PMID 34614138, 2021). "For the current diagnosis of sepsis, commonly used clinical biomarkers involve CRP, WBC, erythrocyte sedimentation rate (ESR), and procalcitonin (PCT)." (PMID 34376255, 2021). "We found that CRP/MPV ratio was significantly higher in the sepsis group compared to the control group." (PMID 34676267, 2021). "The findings of a meta-analysis on a population of critically immunosuppressed patients revealed that CRP was a useful screening tool for sepsis." (PMID 33804790, 2021). "Both WBC counts and CRP levels were higher in the sepsis group, while platelet and Hb levels were lower in the sepsis group." (PMID 34829326, 2021). "The level of PCT was positively correlated with IL-6 only in the sepsis group and CRP only in the infection group." (PMID 34745113, 2021). "Because blood culture is considered the gold-standard test for sepsis, it is logical to compare the efficacy of CRP and PCT to blood culture results." (PMID 34912626, 2021). "Neonates were subjected to sepsis work-up including blood culture, complete blood count and C-reactive protein." (PMID 34706677, 2021). "Many biomarkers have been proposed for diagnosing sepsis, with best evidence available C-reactive protein and Procalcitonin." (PMID 33042929, 2020). "ROC curve analysis was applied to compare the diagnostic value of PBMC miR-10a, CRP, and PCT between infection and sepsis." (PMID 32214905, 2020). "In this study, we aimed to compare the efficacy of NLR as a sepsis marker by comparing it with other markers of sepsis, such as C-reactive protein (CRP), procalcitonin, and the Sequential Organ Failure Assessment (SOFA) score." (PMID 33178505, 2020). "In this population, as shown in the current study, NGAL and CRP are particularly useful for identifying sepsis patients with high specificity and initiating adequate treatment." (PMID 32948801, 2020). "The production of plasma CRP by hepatocytes is controlled in part by IL-6 and consistent with a study of preterm infants with suspected sepsis, our findings are consistent with those showing a positive relationship between CRP and IL-6 plasma levels." (PMID 32479514, 2020). "The other patient (who developed port sepsis) presented with a fever and inadequately low elevation of CRP and PCT levels." (PMID 32086584, 2020). "The respondents reported that CRP was used less to support the decision to postpone antibiotics than to support a diagnosis of suspected sepsis, with 57% (67/117) of respondents using it to postpone the use of antibiotics in less than 25% of cases." (PMID 33114715, 2020).